MMP9 (matrix metallopeptidase 9)
Diseases named in the same sentence as MMP9 in open-access papers (continued):
Sharing a sentence is not in itself a finding about the gene and the disease.
cancer (continued). "Upregulation of MMP-9 induced by CD133+ LCSC contributed to cancer invasion and metastasis." (PMID 37766868, 2023). "MMP-9 has a physiologically low-level expression but is overexpressed in several types of cancers." (PMID 37189693, 2023). "Therefore, we concluded that the LCN2/LOXL2/MMP9 ternary complex promoted the invasion of cancer cells by degrading laminin and type IV collagen." (PMID 37753805, 2023). "Moreover, cryptolepine downregulated WNT3a-induced expression of MMP2 and MMP9 genes, which are involved in cancer cell invasion." (PMID 37513937, 2023). "MMP-2 and MMP-9 have been positively correlated with VM, conferring on cancer cells the capability to remodel the extracellular matrix and degrade the vascular basement membrane, while EphA2 has been reported to be directly involved in the formation of tubular networks." (PMID 37371466, 2023). "Additionally, molecular docking analysis identified potential interactions with cancer-related proteins, such as MMP-9, suggesting a mechanism for DATS action." (PMID 37887119, 2023). "Additionally, we measured the expression of MMP2 and MMP9, which are indicators of cancer metastasis." (PMID 37744277, 2023). "MMP-9 exerts several functions in different phases of cancer progression." (PMID 37525065, 2023). "In particular, MMP-9 expression has been found to be increased in ADAM8-positive cancers." (PMID 36910158, 2023). "The mechanism of MEP1A promoting cancer development may be realized by changing the expression of MMP9, vimentin, and E-cadherin, and participating in the EMT procession." (PMID 37100777, 2023). "The interaction of LCN2 with MMP9 plays a crucial role in modulating the metastatic phenotype of cancer cells, and this interaction correlates with the aggressive behaviour of neoplastic cells in several types of cancer." (PMID 37753805, 2023). "Of all MMPs, MMP-9 is the most essential for cancer-cell invasion and tumor metastasis." (PMID 36903626, 2023). "Given that NF-κB is a key player in inflammation, clusterin may act as a molecular connection between inflammation and cancer by elevating both NF-κB and MMP-9." (PMID 37685987, 2023). "Since SHN3 participates in the regulation of AP-1 or NF-κB transcriptional activity in IL13Rα2-positive cancer cells, a coordinated action of these transcription factors might explain the regulation of MMP9 expression." (PMID 37963919, 2023). "Therefore, MMP-9 is a potentially key molecule in cancer invasion and is considered a target for drug development." (PMID 36870981, 2023). "Thus, it forms an immunosuppressive microenvironment to enhance tumorigenicity, cancer cell motility (via MMP9 expression, PI3K-Akt signaling, and E-cadherin down-regulation), EMT, invasion and metastasis." (PMID 36835413, 2023). "Notably, we detected several critical regulating proteins associated with cancer processes, such as CAMP, MMP9, the S100 family (100A8, S100A9, S100A12), and PRTN3, among the proteins with the most significant increases." (PMID 37231509, 2023). "The abnormal expression of MMP9 is related to the occurrence of many diseases such as cancers." (PMID 37117633, 2023). "However, more recent inhibitors have been discovered through various means, which not only reduced TGM-2 but also other factors such as MMP9, TIMP1 and 2; TNF-α and β, which increases cancer cells’ susceptibility to chemotherapy and inflammation." (PMID 37509081, 2023). "Furthermore, the expression of factors involved in cancer development, such as MMP-9 and interferon γ-inducible protein 30, show the highest upregulation in CLS+ as compared to CLS- human adipose tissue explants." (PMID 36670988, 2023). "The therapy with AAT reduced the numbers of MMP9 (gelatinase B)- positive cells in cancer tissues." (PMID 37532996, 2023).
cancer (continued). "In addition, LPA has been correlated with matrix metalloproteinase-9 (MMP-9) overexpression and MMP-9-associated E-cadherin ectodomain shedding, which results in the disruption of cell–cell junctions between cancer cells." (PMID 37373222, 2023). "Furthermore, we found that most MMPs, including Mmp2, Mmp3, and Mmp9, secreted by cancer cells can degrade ECM to promote cell invasion and migration, were up-regulated in hybrid cells." (PMID 37138326, 2023). "Thus, the role of MMP-9 was purely associated with the degradation of the ECM, which led to the enhancement of carcinoma cell invasion." (PMID 37640804, 2023). "Among the MMPs, MMP-2, and MMP-9 play crucial roles in cancer metastasis." (PMID 35563563, 2022). "The levels of MMP9 in cancer cells may not only influence the proteolysis of TGF‐β, but also the expression of TGF‐β and substances downstream of the TGF signaling pathway." (PMID 36591235, 2022). "The overall results suggest that these hits may also be useful as lead molecules for designing more potent drugs to treat cancer or to act as suitable drug candidates against MMP-9." (PMID 35463960, 2022). "In addition, our results indicated a marked correlation between MMP-9 expression and the macrophage M0 in 28 cancer types." (PMID 35178444, 2022). "MMP-9 plays a key role in the invasion and spread of human cancer cells." (PMID 35878198, 2022). "Some of these genes such as Vascular Endothelial Growth Factor (VEGF), Vascular Endothelial Growth Factor Receptor 1 (VEGFR1), Spondin 1 (Spon1), Transforming Growth Factor beta (TGFβ) or Metalloproteinase 9 (MMP9) were exclusively upregulated in cancer cells from the peritoneal cavity." (PMID 35844581, 2022). "Matrix metallopeptidase 9 (MMP9), a NETosis product, may promote cancer progression by increasing angiogenesis via the production of vascular endothelial growth factor." (PMID 36000086, 2022). "This suggests that in these cancers, patients with high MMP-9 expression may be more suitable for immunosuppressive therapy." (PMID 35178444, 2022). "MMP9 is a well-known metastatic inducer important in cancer progression." (PMID 36010685, 2022). "In addition, members of CAPN family have been reported to facilitate the invasion of THCA by inducing MMP2 and MMP9 secretion, which can contribute to extracellular matrix degradation during cancer cell migration." (PMID 36389799, 2022). "MMP9 is able to trigger intracellular signaling function to promote proliferation of cancer cells." (PMID 35386201, 2022). "Padala and colleagues did not notice any association between MMP9 rs3918242 and stage or type of cancer, lymph node status, the status of ER, PR and HER2/neu, status of distant metastasis." (PMID 36009438, 2022). "What’s more, MMP2 and MMP9 had been reported closed related to migration and invasion of cancers." (PMID 36353142, 2022). "RA-RF also suppressed the metastatic cascade, affecting matrix metalloproteinase-9 (MMP-9) activity and decreasing cancer cell invasion and migration via the AP1 (Activator protein 1), Nuclear factor kappa B NF-κB, and Protein kinase B (Akt) signalling pathways." (PMID 36365218, 2022). "Furthermore, MMPs have a part in other pathophysiological processes; particularly, MMP9 is considered a cancer biomarker." (PMID 36552714, 2022). "Moreover, MMP9 regulates other cellular processes, and its expression and secretion are upregulated in pathological states such as cancer and chronic inflammation." (PMID 36510497, 2022). "Moreover, the expression of MMP-9 was reduced, implying that nordentatin prevented GSK-3 expression, thereby reducing the expression of the MMP-9 protein and thus limiting cancer cell growth." (PMID 35723293, 2022).
cancer (continued). "This may be due to the fact that NGAL forms a complex with both matrix metalloproteinases, (MMP)-2 and MMP-9, in cancer cells, which are suggested to be involved in regulating cell differentiation." (PMID 36293148, 2022). "Additionally, EGCG can inhibit matrix metalloproteinases such as MMP-2 and MMP-9, which are usually elevated in cancer and considered as instruments for degrading the basement membrane and facilitating cell invasion." (PMID 35956766, 2022). "Moreover, an omega-3-rich microenvironment can suppress the secretion of MMP-9 by CAFs, which is beneficial to downmodulate angiogenesis in the cancer stroma and inhibit cancer cell metastasis." (PMID 36422541, 2022). "Furthermore, MMP-2 and MMP-9 can remarkably affect angiogenesis in malignant tumors by activating VEGF." (PMID 35295962, 2022). "However, there is a lack of comprehensive pan-cancer studies on the relationship between MMP-9 and cancer prognosis and immune infiltration." (PMID 35178444, 2022). "Moreover, the effect of Ap-CH-BSA-FANPs on cancer metastasis was revealed by the decrease in MMP9 expression." (PMID 35745733, 2022). "Moreover, NGAL forms complexes with both MMP-2 and MMP-9 in cancer cells, which are thought to be involved in regulating cell differentiation." (PMID 36293148, 2022). "Thus, epithelial mesenchymal transition (EMT) marker proteins (SNAIL, fibronectin, E-cadherin, MMP-1, MMP-9 and vimentin) as well as cancer cell migration and invasiveness processes were analyzed in the presence of E2." (PMID 36419896, 2022). "All these results revealed that GsRb1 might be a potential MMP-9-specific inhibitor with therapeutic effects on myocardial remodeling and cancer metastasis." (PMID 36432152, 2022). "MMP-9 is an essential component in cancer invasion and metastasis, and the upregulation of MMP-9 expression may lead to the release of VEGF and the formation of angiogenesis." (PMID 36080631, 2022). "The role of MMP-9 in inducing EMT is predominantly promoting cancer metastasis." (PMID 35586209, 2022). "MMP-9 expression can be unusually high in most cancers, and it is regulated in a complicated way." (PMID 35463960, 2022). "Interestingly, concentrations of MMP-9 were higher than MMP-2 levels (p < 0.0001) when both gelatinases were compared in cancer groups." (PMID 36213817, 2022). "In general, L-theanine could induce cancer cell apoptosis through the mitochondrial pathway, inhibiting the EGFR, NF-κB, and other signaling pathways, downregulating MMP9, or upregulating Smad2 in cancer treatment." (PMID 35445053, 2022). "High-LPCAT1 expression could inhibit STAT1 expression, up-regulate CyclinD1, CyclinE, CDK4 and MMP-9, and decrease p27kip1 to promote cancer progression in HCC." (PMID 36307879, 2022). "MAPK-regulated MMP-9 in cancer cells has been reported in many studies." (PMID 35563563, 2022). "These cells can also mediate cancer cell invasion by secreting matrix metalloproteinase-9 (MMP9)." (PMID 35493456, 2022). "Furthermore, we found that MMP-9 expression was correlated with immune infiltration levels in multiple cancer types, especially ACC and KIRC." (PMID 35178444, 2022). "In addition, MEL selectively inhibits expression of matrix metalloproteinase-9 (MMP-9), which plays an important role in the migration of cancer cells via down-regulating activator protein-1 (AP-1) and NF-κB expression." (PMID 35053266, 2022). "Furthermore, deflamin resulted not only in a significant reduction in MMP-2 and MMP-9 activity but also in impaired cancer cell migration and invasion in vitro." (PMID 36551666, 2022). "P38MAPK-mediated induction of MMP-9 expression may contribute, in part, to the promotion of cancer cell invasion by SNCG." (PMID 35637967, 2022).
cancer (continued). "The location score was significantly higher in the cancer tissue and metastatic lymph nodes compared with the healthy tissue, indicating abnormal histopathological expression in the cancer tissue such as intracytoplasmic/intranuclear localization of the MMP-9." (PMID 36242015, 2022). "Additionally, the Ras/Raf/ERK/MMP9 cascade in “proteoglycans in cancer” is involved in cell proliferation, survival, and angiogenesis." (PMID 35566048, 2022). "MMP-9 significantly affected the prognosis and metastasis of various cancers." (PMID 35178444, 2022). "Interestingly, MMP9 appears to have a strong positive correlation with ClC-3, which regulates the extracellular environment and promotes the migration and invasion of cancer cells through multiple pathways of upregulation of MMP9 expression." (PMID 36277193, 2022). "MMP-9 enhances the metastasis of cancer cells by degrading collagen proteins of the ECM." (PMID 36605288, 2022). "The overexpression of MMP-9 has often been observed in different malignant tumors." (PMID 35955456, 2022). "The most important of these is MMP9, which is elevated in serum and tissues associated with tumors, and is involved in the degradation of the ECM to facilitate the migration of immune cells in cancer." (PMID 36591235, 2022). "The discovery of a new selective MMP-9 inhibitor may be useful in cancer prevention and treatment in the future." (PMID 35723293, 2022). "Furthermore, p38MAPK inhibition abrogates the promotion of MMP-9 expression and cancer cell invasion by SNCG." (PMID 35637967, 2022). "Combination of EGCG and Dacarbazine enhanced the efficacy of Dacarbazine by inhibiting activities of FAK and MMP-9, as well as proliferation and/or metastasis of cancer cells, in which the effective dosage of Dacarbazine was reduced, resulting in less potential cytotoxicity to the healthy cells." (PMID 36545470, 2022). "Consistent with previous literature showing that increased MMP9 expression promotes cancer cell migration, invasion, and metastasis, MMP9 mRNA levels were enhanced in N1 + and advanced-stage (III + IV) tumors when compared to those in N0 and the earlier-stage (I + II) tumors, respectively." (PMID 35589683, 2022). "The gelatinase MMP-9 plays a crucial role in cancer development and progression." (PMID 35954442, 2022). "MMP-9 is highly expressed in a variety of highly invasive malignant tumors." (PMID 35361045, 2022). "Finally, silencing of TSPAN14 in these non-metastatic cancer cells caused an increased expression of matrix-degrading enzymes MMP-2 and MMP-9, followed by an elevated capacity of cancer cells to degrade gelatin." (PMID 36143328, 2022). "Finding the drugs which can control the activity of MMP-9 is an important area of cancer research." (PMID 35463960, 2022). "In addition, vitamin D also inhibited MMP-9 secretion by extracellular matrix, further reducing cancer cell migration." (PMID 35498406, 2022). "MMP9 is highly expressed in cancer and played crucial roles in carcinogenesis and progression." (PMID 36307882, 2022). "We concluded that hsa-miR-30a-3p significantly suppresses MMP2 and MMP9 expression and cell invasiveness in BC, which may become a potential tool of miRNA-based cancer therapy targeting MIBC." (PMID 35449123, 2022). "MMP9 is primarily expressed by inflammatory cells during complaints such as RA and cancer." (PMID 35207422, 2022). "As a biomarker for numerous cancers, MMP9 has versatile roles." (PMID 35992852, 2022). "Furthermore, TGF-β-mediated signaling induces expression of MMPs, notably MMP2 and MMP9, potentially facilitating the migration and invasion of cancer cells." (PMID 36012449, 2022). "Similarly, tumstatin, which is a 28 kDa matrikine released by MMP9 from the α3-chain of type IV collagen (COL4α3), was found to suppress cancer growth through αvβ3 integrin-mediated antiangiogenic activity." (PMID 35406619, 2022). "Studies demonstrated EGCG to be an MMP-9 inhibitor and prevent the invasion of cancer." (PMID 36362132, 2022).
cancer (continued). "Furthermore, gene ontology analysis (STRING) was performed for each protein cluster to assess the matching of proteins with the KEGG pathways to identify the role of LCN2, SLC22A17, and MMP9 genes in cellular processes and cancer pathways." (PMID 36211450, 2022). "Besides, EMT is closely related to over-expression of MMP2 and MMP9 that are also correlated with cancer cell invasion and metastasis." (PMID 36338704, 2022). "The recruitment and activation of proteases such as MMP2 and MMP9 at invadopodia sites could promote the degradation of ECM so as to provide traction for cancer invasion and metastasis." (PMID 35957827, 2022). "Consequently, regulation of MMP-2 and MMP-9 are crucial for preventing cancer invasion and metastasis." (PMID 35458783, 2022). "The goal is to develop a new generation of therapies that target MMP9 for the treatment of cancer." (PMID 35406619, 2022). "MMP9 (gelatinase B) stimulates or inhibits the process of degradation of the extracellular matrix (ECM), and its overexpression is associated with various cancers, as well as with acute and chronic inflammatory and infectious diseases." (PMID 35197508, 2022). "MMP-2 is an anti-cancer drug target in several aggressive tumors, whereas MMP-9 inhibitors may prove useful in treating cancer in its early stages as well as multiple autoimmune diseases." (PMID 35955688, 2022). "Furthermore, alcohol can directly upregulate the expression of vimentin and matrix metalloproteinases MMP-2, MMP-7, and MMP-9, which are known to promote an epithelial–mesenchymal transition, cancer cell aggressiveness, and extracellular remodelling." (PMID 35276890, 2022). "Moreover, CCL2–CCR2 signaling enhances metalloproteinase MMP2 and MMP9 production in human chondrosarcoma and hepatoma cells, which elicits detrimental effects on cancer cell invasion and motility." (PMID 35408440, 2022). "STMN1 knockdown upregulated MMP1 and MMP9, responsible for cancer invasion." (PMID 36188577, 2022). "That study found that MMP-9 was significantly upregulated in twelve of the fifteen cancer types." (PMID 35742125, 2022). "Indeed, our results concerning the bioactivities of both beverages show that both lupin and chickpea-based beverages do present a strong inhibitory activity on MMP-9 while reducing cancer cell migration." (PMID 35911116, 2022). "The relationship between MMP-9 and immune cells has been reported in various malignant tumors." (PMID 35178444, 2022). "However, data concerning a correlation between high MMP-2 and MMP-9 levels and carcinoma types according to the Lauren’s classification were contradictory." (PMID 35163805, 2022). "There is accumulating evidence that MMP-9 potentiates various cancer metastasis." (PMID 34158560, 2021). "MMP-2 and MMP-9 play a key role in cancer migration and invasion." (PMID 34356663, 2021). "It has been demonstrated that NET-associated serine proteases such as NE could act as alternative enzymes for processing inflammasome-related IL-1β and IL-18, which subsequently leads to the modulation of PGRN inactivation and MMP-9 activation in cancer." (PMID 34476216, 2021). "Among the MMPs family, MMP2 and MMP9 are involved in the breakdown of extracellular matrix in normal processes, so they are closely associated with the cancer cell migration." (PMID 35059399, 2021). "Lymphocyte-specific protein tyrosine kinase (LCK) phosphorylates Tyrosine-342 of FOXP3 and upregulates its expression resulting in decreased Matrix metalloproteinase 9 (MMP9), S-phase kinase-associated protein 2 (SKP2), and Vascular endothelial growth factor A (VEGF-A) levels in cancer cells." (PMID 33614551, 2021). "In vitro studies have also demonstrated the impact of P. gingivalis and F. nucleatum on the upregulation of matrix metalloproteinases, including MMP-2, MMP-3, and MMP-9, which degrade the extracellular matrix and the basement membrane enabling cancer cells to invade and translocate to other sites." (PMID 34299675, 2021).